RBMXL2 (RBMX like 2)
Description:
RNA-binding protein involved in alternative splicing in the testis during spermatogenesis.
Synonyms: HNRNPGT; HNRNPG-T; HNRPGT
Tractability: PROTAC: ubiquitination databases record sites on it.
Gene: Protein-coding gene on chromosome 11 (7,088,998 to 7,091,148, forward strand). Ensembl gene ENSG00000170748.
Subcellular location: Nucleus
Gene Ontology:
Molecular function: mRNA binding; snRNA binding; nucleic acid binding; RNA binding
Cellular component: nucleus; precatalytic spliceosome
Genetic constraint (gnomAD): Loss-of-function variants: 3 observed, 2.58 expected, observed/expected ratio (o/e) 1.16, 90% interval 0.48 to 1.89. That is too few expected variants to judge how well the gene tolerates losing a copy. Missense variants: 658 observed, 560.36 expected, observed/expected ratio (o/e) 1.17, 90% interval 1.1 to 1.25. Synonymous variants: 313 observed, 245.49 expected, observed/expected ratio (o/e) 1.27, 90% interval 1.16 to 1.4.
Homologues: Orthologues: chimpanzee RBMXL2 (99% identical), macaque RBMXL2 (96% identical), mouse Rbmxl2 (79% identical), rat Rbmxl2 (79% identical). Paralogues in human: RBMX (73% identical), RBMXL1 (69% identical), RBMXL3 (66% identical), RBMY1B (48% identical), RBMY1A1 (48% identical), RBMY1D (48% identical), RBMY1E (48% identical), RBMY1F (48% identical), RBMY1J (48% identical), CIRBP (24% identical), RBM3 (21% identical), MSI2 (21% identical), and 24 more.
Diseases named in the same sentence as RBMXL2 in open-access papers:
RBMXL2 is named in the same sentence as 7 diseases in open-access papers, as found by Europe PMC text mining. Sharing a sentence is not in itself a finding about the gene and the disease. The quoted sentences say what the papers report.
Azoospermia (2 papers, 2019). Absence of any measurable level of sperm,whereby spermatozoa cannot be observed even after centrifugation of the semen pellet. "Furthermore, disruptions in RBMXL2 expression and localization in human testes are associated with azoospermia in men." (PMID 30893341, 2019). "Asterisk indicates lumen (note lumen is empty in Rbmxl2-/- section indicative of azoospermia, but contains multiple cells in the wild type)." (PMID 30674417, 2019).
male infertility (2 papers, 2019 to 2024). The inability of the male to effect fertilization of an ovum after a specified period of unprotected intercourse. "In addition, a recent case report revealed that deleterious variants within the RBMXL2 gene have the potential to induce male infertility by contributing to a complete meiotic arrest, potentially by disrupting the normal trajectory of gene expression." (PMID 38886667, 2024). "Taking all these results into consideration we suggest that RBMXL2 has a key role controlling the meiotic transcriptome, and suggest that human male infertility caused by loss of RBMXL2 or its paralog RBMY may be associated with germ cell type-specific cryptic splicing." (PMID 30674417, 2019). "A further connection to male infertility is that RBMXL2 belongs to the same gene family as RBMY, which was historically the first human Y chromosome infertility gene identified in the search for the AZF (AZOOSPERMIA FACTOR) gene." (PMID 30674417, 2019).
breast carcinoma (1 paper, 2018). "We found RBMS2, RBMS3, RBMXL2 were the significantly differently expressed RBMs in breast cancer." (PMID 30514345, 2018). "RBMS3 was reported to have a low expression in breast cancer tissues and cell lines and inhibit the proliferation and metastasis of breast cancer and RBMXL2 was mainly expressed in testis tissue while it had a very low expression in both breast tissue and cancer in Human Protein Atlas database." (PMID 30514345, 2018). "RBMXL2 had a very low expression in both breast tissue and cancer in TCGA database and RBMS3 was reported to be a tumor suppressor in breast cancer." (PMID 30514345, 2018).
infertile (1 paper, 2013). "Haploinsufficiency of Rbmxl2 causes infertility in mice, and Sam68 null mice are infertile." (PMID 24038356, 2013).
RBMXL2 also shares sentences with these, for which no sentence is quoted: tumor (2 papers); cancer (1); seminoma (1).